IL10 (interleukin 10)
Diseases named in the same sentence as IL10 in open-access papers (continued):
Sharing a sentence is not in itself a finding about the gene and the disease.
infection (continued). "IL-10 production was critical for S. aureus persistence during craniotomy infection, as evidenced by the significant reduction in bacterial burden in the brain and galea of IL-10 KO mice compared to WT animals." (PMID 37179295, 2023). "IL-10 is an anti-inflammatory cytokine activated in an early phase of infection to suppress proinflammatory cytokines, thereby avoiding excessive immune responses and consequent tissue damages." (PMID 37600000, 2023). "Zi-treated mice showed reduced inflammatory scores in the lungs, reduced dendritic cell-producing tumor necrosis factor (TNF), and increased neutrophil-producing interleukin (IL)-10 in the lungs 3 days after infection (dpi), the peak of lung damage." (PMID 37896826, 2023). "Chromatin immunoprecipitation (ChIP) assays further demonstrated enhanced recruitment of STAT3 to the IL-10 promoter upon LDPm infection." (PMID 37202419, 2023). "SAB IL-10−/− mice were perorally subjected to either oral LEM-EO or COR-EO via the drinking water starting from day 7 before infection." (PMID 37065112, 2023). "S. aureus burden was reduced in Mrp8CreIL-10 fl/fl but not CX3CR1CreIL-10 fl/fl mice that was reversed following treatment with exogenous IL-10, suggesting that granulocyte-derived IL-10 was important for promoting S. aureus craniotomy infection." (PMID 37179295, 2023). "Nonetheless, secretion of the anti-inflammatory cytokine IL-10 was also reduced after inhibition of glycolysis in human CD1c+ mDCs upon infection with BCG, like murine BMDCs stimulated with LPS." (PMID 37475964, 2023). "At this stage, Th17 cells can secrete IL-9 and IL-10, and IL-10 exerts antagonistic effects on Th17 cells pathogenicity during infection or inflammation." (PMID 37680632, 2023). "In relation to IFN-γ and IL-10, infection increased the levels of both cytokines in the group treated with letrozole, and their concentration decreased inversely proportionally to testosterone levels." (PMID 37384220, 2023). "claimed a Th1 origin for TR1 cells in a chronic Plasmodium infection model, solely on the basis of presence of IL-10-expressing cells within the infection-induced Th1 pool, and on the assumption that TR1 cells are simply IL-10/IFNγ-co-expressing cells." (PMID 37818381, 2023). "At the same time, numerous pathogens induce IL-10 up-regulation during the infection and exploit the immunosuppressive activity of this cytokine to escape host immune system and promote a microenvironment that favors their tolerance and long-term survival." (PMID 37359549, 2023). "In line with this, the percentage frequency of CD4+ T cells that produce IFN-γ, IL-17 or IL-10 in the splenocytes remained low in BA.5 infection as compared to ancestral Wuhan-Hu-1, but were found to be comparable to that of parental B.1.1.529 infected mice." (PMID 37704701, 2023). "In experimental models of cutaneous leishmaniasis (CL), the immune response is inhibited at the infection site by IL-10-secreting CD4+ T cells in C57BL/6 (Th1-dominant response) or BALB/c (Th2-dominant response) mouse models." (PMID 37235324, 2023). "Even though PGE2 was able to increase IL-10 production in uninfected macrophages, the levels produced were apparently insufficient to regulate the inflammatory response observed during infection." (PMID 37729084, 2023). "Infection also elicits a relatively high number of eosinophils (personal observations) which can secrete IL-10 and IL-6 cytokines." (PMID 36839863, 2023). "The IL-10 levels in Rongchang pigs remained relatively constant after infection with two PRRSV strains of different pathogenicity." (PMID 37920268, 2023). "Infection with L. major expressing the chimeric protein 2 W (Lm-2W) also reported IL-10 producing 2W-specific Th1 cells." (PMID 38114497, 2023).
infection (continued). "Stimulation of PBMCs isolated from Nigerian adolescents and adults with PPD showed similar IFN-γ production but increased IL-4 and IL-10 secretion in malaria/TB co-infected subjects compared to individuals with TB mono-infection." (PMID 38089636, 2023). "Unlike mucosal sites in the respiratory tract, ongoing viral replication in this model occurs primarily in the SGs, facilitated by the induction of CD4+ T cells that produce IL-10, which peak on day 14 post-infection (p.i.)." (PMID 37440306, 2023). "In the nasal turbinates, Wuhan/ΔORF7ab infection also induced a higher expression of Mx2, but also Il-6, Cxcl10, Tnf-α and Il-10." (PMID 37495586, 2023). "The release of four key mediators (MCP-1, TNF, IL-10, and IL-6) into the supernatant of cell cultures was measured before and after infection with BCG or stimulation with MDP." (PMID 36972292, 2023). "Granulocytes (neutrophils and G-MDSCs) were the major producers of IL-10 during craniotomy infection." (PMID 37179295, 2023). "CD8+ T cells expressing markers of exhaustion such as PD-1+ TIM3+ increase over the infection and this scenario seems to be related to IL-10 blood levels." (PMID 37662901, 2023). "H8 effectively inhibited WT growth during macrophage infection and elicited significantly higher levels of IL-10 in WT-infected macrophages vs. untreated macrophages." (PMID 38196634, 2023). "Next, to characterize the immune profiles of CD138+IL10+ PB-PCs induced in a normal response to infection, we carried out gene set variation analysis (GSVA) with pre-defined gene sets comprising cellular and inflammatory pathways." (PMID 38155972, 2023). "Clustering identified a group of inflammation-related cytokines secreted on the apical side in response to infection, including IL-5, IL-17, IL-10 and IL-1RA." (PMID 37822359, 2023). "The ability of AMP to induce IL-10 production in addition to its strong antimicrobial activity would benefit the outcome of infection therapy." (PMID 36978418, 2023). "Levels of IFN-γ, TNF-α, IL-6, and IL-10, which are important for the activation of protective immunity, were significantly increased at the early stage of ΔPbMAP1 infection." (PMID 37563696, 2023). "The results of Western blot revealed that IBV/S9-MD infection increased protein expression of inflammatory factors, IL-10 and LI-1β in mouse lung tissues." (PMID 37919750, 2023). "Conversely, IL-4 and IL-10 transcriptional levels were reduced in the livers of the mice treated with anti-PD-L2 during the late stage of infection (9–12 weeks post-infection)." (PMID 36668953, 2023). "In this study, we provide both proof of the concept, and pharmacological evidence for a protective role of IL-10 ascending infection-mediated PTB by leveraging a novel mode of exosomal delivery of the anti-inflammatory cytokine." (PMID 37600782, 2023). "It is therefore imperative to investigate the potential of urinary IL-6 and IL-10 in morbidity monitoring under low infection endemicity setting." (PMID 37018184, 2023). "In previous work, IL-10 was elevated in the blood at 18 h post-burn and infection and remained elevated until the mice succumbed." (PMID 37929965, 2023). "Specifically, IL-10 derived from Foxp3−CD4+ T cells is a critical source of this cytokine during infection." (PMID 37843306, 2023). "IL-10 production was most robust in granulocytes that invaded the brain and galea at days 7 and 14 post-infection, whereas expression in monocytes and microglia was lower." (PMID 37179295, 2023). "Simultaneously with the increase in the levels of proinflammatory cytokines, a significant decrease in the expression of IL10 at the early stage of infection has been reported by previous studies." (PMID 37620551, 2023). "Macrophages and supernatants were collected after different times (0h, 4h, 12h, 24h and 48h) of B. abortus-infection, and mRNA expression of macrophage M1 (Tnfα, Nos2 and Il1β) and M2 (Tgfβ, Arg1, Il10) polarization marker genes were detected by RT-qPCR." (PMID 37325614, 2023).
infection (continued). "IL-10 plays essential roles in maintaining tissue homeostasis during infection and inflammation by restricting excessive inflammatory responses." (PMID 36916913, 2023). "Further, inhibition of DKK1 in vivo or platelet depletion resulted in reduction in IL-4, IL-10 and L. major parasite burden as well as cellular recruitment to the draining lymph node and site of infection." (PMID 37885890, 2023). "IL-10 is an anti-inflammatory cytokine that plays a key role in infections by preventing inflammatory damage to host tissues." (PMID 36972292, 2023). "To explore the mechanism of AIEC contributing to intestinal fibrosis, we developed a long-term and recurrent AIEC infection model using IL-10−/− mice to mimic the chronic intestinal inflammation of patients with CD." (PMID 36945126, 2023). "IL-10, an anti-inflammatory cytokine, showed a gradual increase in mice given Salmonella alone and reached the highest level on day 6 post-infection." (PMID 36361621, 2022). "Conversely, anti-inflammatory cytokines, such as IL-4, IL-5, IL-10 and IL-13, among others, seem to act to regulate the Th1-type response and favoring the development of infection." (PMID 35891310, 2022). "The mRNA expression of il1-β and il-10 was found to increase in infected animals immediately after infection and were maintained along sampling times." (PMID 35163486, 2022). "The percentage of E. histolytica infection was higher among patients who had a low concentration of IL-10 (68.1%), while in patients with high levels of IL-10, the percentage of the infection was lower (58.2%)." (PMID 36678367, 2022). "More IL-10-producing CD8T cells were induced in PyNL-vaccinated mice after infection with PbA (Vac PbA: 16.9%, 1052 × 103 cells, mean value) than in the control mice (approximately 8-fold more than in unvaccinated control)." (PMID 35632518, 2022). "At 14 d post-infection, serum levels of IL-12 and IL-10 were observed to be lower in ZIL-treated mice while none of the remaining groups showed any differences in the serum cytokine production as compared to their respective control groups." (PMID 36039381, 2022). "Our previous results revealed that TLR4‐MyD88 signalling controls IL10 production following Kp52145 infection." (PMID 36337046, 2022). "Such MIF-mediated pathological side-effects during infection can be alleviated by pathogen-elicited IL-10 production." (PMID 35464430, 2022). "On the other hand, the level of IL-10 production was low throughout the infection with P. chabaudi as in accordance with low parasitaemia." (PMID 35109868, 2022). "During the inflammatory period, macrophages secrete pro-inflammatory factors (IL-1β, TNF-α, IL-6, etc.)and anti-inflammatory factors (IL-10) to clear the necrotic tissue and prevent infection at the wound site." (PMID 35877710, 2022). "Following infection, AP stimulates the production of proinflammatory cytokines: IL-6, IL-8, IL-10, and TNF-alfa, which lead to recruitment of neutrophils, degranulation, and consequently tissue injury." (PMID 35889152, 2022). "Here we show that, during infection with the helminth H. polygyrus, the intestinal immune response involves both Th1 and Th2 activity and intestinal IL-10 balances these responses, promoting Th2 cytokine expression by limiting local Th1 cells." (PMID 35428872, 2022). "The poor ability of the RA larvae to induce PGE2 and IL10 has been proposed to be responsible for differential capacity for infection compared to normal larvae." (PMID 35396684, 2022). "In contrast, increased resistance to P. chabaudi adami infection in Mif -/- mice was associated with increased IFN-γ production and reduced IL-4 and IL-10 in early infection." (PMID 36093199, 2022). "Infection activates the sympathetic nervous system, and the latter downregulates or inhibits the expression of IL-10." (PMID 35999492, 2022). "We first evaluated the impact of IL-10 and TGF-β on moMΦ susceptibility to infection with ASFV strains of different virulence." (PMID 35215110, 2022).
infection (continued). "Surprisingly, significant differences in the levels of serum IFN- γ and IL-10 between co-infected survival groups (day 4 and 6 challenge) indicated that even a two-day delay in challenge infection was crucial for the resulting pathology." (PMID 35719355, 2022). "Th2 cells, CD8+ T cells, B cells and myeloid cell populations have all also been shown to be capable of releasing IL-10 during infection (reviewed in34)." (PMID 35428872, 2022). "In children with hematological malignancies, greater expression levels of IL-6 and IL-10 predict infection, and their high expression indicates the severity of the infection." (PMID 35463642, 2022). "In a multivariate model testing both status and day, membership in the E16.5 group was a significant predictor for Ifnγ, Tnf, Il1β, Il10, and Cox2 abundance (p ≤ 0.0306), while holding infection status constant." (PMID 35312688, 2022). "Cytokines are responsible for all the symptoms and pathological manifestations during infections, and IL-10 and IFN-γ are involved to moderate this process." (PMID 35719355, 2022). "Infection with R-LD leads to aggressive infection accompanied by higher production of IL-10 and TGF-β compared with S-LD infection." (PMID 35925884, 2022). "Numerous inflammatory cells, mainly macrophages, dendritic cells, polymorphonuclear neutrophils, and inflammatory cytokines (TGF-β, TNF-α, IL-1β, IL-6, IL-10, IL-12, and IL-23), were activated in the early stages of infection." (PMID 36233337, 2022). "In contrast, only the mix of pp71 and US3 proteins generated IL-10 responses in these donors, which shows that these responses were detectable from early time points post infection and are maintained in the long-term memory responses." (PMID 36558866, 2022). "Surprisingly, E. granulosus s.s. infection resulted in increased IL-10 expression in hepatic or splenic CD8+ T cells from CD4 knockout mice and decreased granzyme B or IFN-γ expression." (PMID 36046744, 2022). "IL-10 levels also increased in both groups, as compared to levels detected at 3 hours post infection, but in contrast increased levels were observed in the treated group as compared to levels produced by untreated cells." (PMID 35145518, 2022). "Following ART initiation, plasma IL-10 rapidly decreased (12.01 ± 1.041 pg/mL at d135 p.i.)and stabilized at levels still higher (12.06 ± 1.28 pg/mL at d259 p.i.)as compared with pre-infection." (PMID 35230978, 2022). "In another study, IL-10 levels in the serum were significantly elevated at 21 and 28 days after infection, and IL-10 production was significantly elevated in spleen cells at 21, 28, 35, and 42 days after infection in a Brucella infection rat model." (PMID 36140754, 2022). "Infections with Leishmania parasites, another member of the Trypanosomatidae family, result in a similar dual role of IL-10, whereby a trade-off must be made between effective parasite killing and avoidance of an exaggerated pro-inflammatory response." (PMID 35464430, 2022). "During the course of the infection, IL-10 levels remained elevated until 30 dpi, but from the onset of the chronic phase (60 dpi), there was a decrease in IL-10." (PMID 35720419, 2022). "The evaluations of cytokine mRNA expression indicated that, both the Th1 (IFN-γ, TNF-α, IL-12) and the Th2 (IL-4 and IL-10) types of cytokines were differentially upregulated during the early stage of infection." (PMID 35215986, 2022). "This was linked to reduced serum concentrations of the pro-inflammatory cytokines (IFNɣ, TNF, and IL-6) and an increase in the IL-10 serum concentration, especially during the chronic stage of infection." (PMID 35464430, 2022). "A study examining the response to Pseudomonas corneal infection reported a significant increase in IL10 24 h after infection in whole eyes compared to corneas and emphasized the need to consider whole ocular responses, not only corneal responses." (PMID 35456761, 2022).
infection (continued). "Our results suggest that the immune response profile in IL-32γTg mice, after 28 days of infection, became more regulated due to the high production of IL-10 observed in the heart, and this was due to a possible induction of IL-32β." (PMID 35097133, 2022). "It has previously been shown that S. aureus promotes IL-10 responses in order to persist during chronic systemic infection and biofilm models of infection." (PMID 35776778, 2022). "IL-10, known as one of the anti-inflammatory cytokines, has a central role in infection by limiting the immune response to pathogens, thereby preventing damage to the host." (PMID 35967581, 2022). "Our data show that, during infection with the intestinal helminth parasite H. polygyrus, IL-10 is a striking feature of the immune response in the infected intestinal tissue." (PMID 35428872, 2022). "We examine the levels of TNF-α, IL-12, IFN-γ, IL-2, TGF-β, IL-10, IL-17, and IL-6 in lung lysates obtained from M. tb-infected mice at different timepoints post-infection." (PMID 35453358, 2022). "More detailed time-course of infection studies will be needed to relate IL-10 activation/expression with changes in other cytokine levels (e.g., IL-1β and TNFα)." (PMID 35911725, 2022). "Previous studies showed that during the infection by intracellular parasites, including T. cruzi, IL-10 acts by down-regulating T-cell responses favoring the parasite persistence." (PMID 35812458, 2022). "Both Th1 (IFN-γ, TNF-α, IL-12) and Th2 (IL-4 and IL-10) types of cytokines were differentially upregulated during the early stage of infection; however, the Th1 cytokines exhibited stronger activation before 8 hpi compared to those of the Th2 cytokines." (PMID 35215986, 2022). "This included peak Th2 cytokine potential at approximately 8 wks post infection, and increased IL-10 during chronicity, particularly in the liver and MLNs." (PMID 35958580, 2022). "IL-10 is a pleiotropic anti-inflammatory cytokine crucial to control pro-inflammatory responses during infections, thus preventing inflammatory pathologies." (PMID 35464430, 2022). "By blocking PGE2 receptors (EP2 and EP4), this delayed reaction was achieved to decrease IL-10 and increase IL-12 early after infection." (PMID 35396684, 2022). "In contrast to this beneficial role, we recently found that systemic IL-10 induced at 3 days post-infection exacerbates S. pneumoniae lung infection." (PMID 35680890, 2022). "Of note, well in line with the normal course of infection in conditional NfkbidΔLysM mice, IL-10 levels as well as any other cytokine tested (data not shown) were not affected by IκBNS-deficiency exclusively in myeloid cells." (PMID 36618344, 2022). "These alterations in the kinetics of monocytes, neutrophils, and CD4+ T cells coincided with a significant increase in serum concentration of TNFα, IFNγ, CXCL10, and IL-10 early after infection." (PMID 36466866, 2022). "In this context we discovered that IκBNS-deficient mice fail to produce any significant quantities of IL-10, both in the steady state and during infection." (PMID 36618344, 2022). "Biofilm infection induced leucocyte infiltration and elevated interferon-γ and interleukin-10 in scaffolds, increase of size and weight of spleen and high systemic pro-calcitonin concentrations." (PMID 36528648, 2022). "In both B6 (normal levels of IL-10) and pMT-10 (high levels of IL-10) BCG-vaccinated mice, the control of infection was associated with a rapid accumulation of Ag85b-specific CD4+ T cells in the lungs." (PMID 35935958, 2022). "The cytokines MCP-1, IFN-γ, TNF-α, IL-10, IL-12, andIL-6 were measured in culture supernatants 4- and 48-hours post-infection." (PMID 35910486, 2022). "The proportion and number of IL-10-producing CD4T cells decreased after PbA infection in unvaccinated mice (naive mice: 4.1%, 466 × 103 cells vs. control PbA: 2.9%, 254 × 103 cells, mean value)." (PMID 35632518, 2022).